GLIPR1 (GLI pathogenesis related 1)
Diseases named in the same sentence as GLIPR1 in open-access papers (continued):
Sharing a sentence is not in itself a finding about the gene and the disease.
lung adenocarcinoma (2 papers, 2017 to 2021). A carcinoma that arises from the lung and is characterized by the presence of malignant glandular epithelial cells. "The underlying mechanism of upregulated GLIPR1 cell growth stimulation has been studied in human lung adenocarcinoma A549 cells and correlates with inducing anti-apoptotic Bcl-2 protein expression." (PMID 34142021, 2021). "In human lung adenocarcinoma A549 cells, upregulation of GLIPR1 stimulated cell proliferation by inducing the increased expression of Bcl-2, thus increasing resistance to the chemotherapeutic drug cisplatin." (PMID 34142021, 2021). "Compared to human lung adenocarcinoma A549 cells, the mRNA and protein expression of GLIPR1 were significantly increased in DDP-resistant A549/DDP cells (p < 0.05)." (PMID 28771580, 2017). "In this study, we examined the expression of GLIPR1 in DDP-sensitive and -resistant human lung adenocarcinoma A549 and human large cell lung cancer H460 cells and the role of GLIPR1 in mediating the resistant of A549/DDP and H460/DDP cells to DDP." (PMID 28771580, 2017). "In the present study, the results showed that compared with human lung adenocarcinoma A549 cells, the mRNA and protein expression of GLIPR1 were significantly increased in DDP-resistant A549/DDP cells." (PMID 28771580, 2017). "However, the expression and function of GLIPR1 in mediating DDP resistance in human lung adenocarcinoma A549/DDP and human large cell lung cancer H460/DDP cells has not yet been reported." (PMID 28771580, 2017). "However, the role of GLIPR1 in mediating DDP resistance in human lung adenocarcinoma A549/DDP and human large cell lung cancer H460/DDP cells has not yet been reported." (PMID 28771580, 2017). "To investigate the potential role of GLIPR1 in the development of chemotherapeutic drug resistance, we firstly compared the expression levels of GLIPR1 in DDP-sensitive and -resistant lung adenocarcinoma A549 cells." (PMID 28771580, 2017).
metastatic melanoma (2 papers, 2013 to 2016). A melanoma that has spread from its primary site to another anatomic site. "GLIPR1 was variably expressed in metastatic melanoma and elevated GLIPR1 levels were correlated with increased invasive potential." (PMID 26988096, 2016). "Based on the data presented here, future studies will focus on identifying whether GLIPR1 levels and/or promoter methylation status may be a clinically beneficial marker of metastatic melanoma phenotype." (PMID 24010123, 2013).
myeloma (2 papers, 2018 to 2020). "In this study, we demonstrate that plasma cell expression of GLIPR1 is reduced in the majority of myeloma patients and Glipr1 expression is lost in the 5TGM1 murine myeloma cell line." (PMID 31995627, 2020). "However, it remains possible that the down-regulation of GLIPR1 may cooperate with other genetic lesions to promote the development of myeloma." (PMID 31995627, 2020). "Therefore, we hypothesised that GLIPR1 may have tumour suppressor activity in multiple myeloma." (PMID 31995627, 2020). "Taken together, our results suggest that GLIPR1 is unlikely to be a potent tumour suppressor in multiple myeloma." (PMID 31995627, 2020). "However, overexpression of GLIPR1 in a human myeloma cell line did not affect cell proliferation in vitro." (PMID 31995627, 2020).
Obesity (2 papers, 2016 to 2020). Accumulation of substantial excess body fat. "The genes within 2 Mb of the signal, include RP11-81H3.2, CAPS2, GLIPR1, GLIPR1L1, GRLPR1L2, and KRR1, none of which is an obvious candidate gene for involvement in obesity or T2D." (PMID 27623749, 2016).
thyroid cancer (2 papers, 2021 to 2024). "In one study of induced thyroid cancer in male mice, gonadectomy led to an upregulation of tumour-suppressor genes, Glipr1 and Sfrp1 suggesting that testosterone promotes thyroid cancer progression through the suppressed expression of these genes." (PMID 34572888, 2021).
amyloidosis (1 paper, 2020). A disorder characterized by the localized or diffuse accumulation of amyloid protein in various anatomic sites. "Given that the GLIPR1 tumour suppressor gene was found to have significantly reduced expression levels in PCs from patients with amyloidosis and to be deleted in 9.4% of MM patients, we hypothesised that the expression of GLIPR1 may also be down-regulated in the malignant PCs of MM patients." (PMID 31995627, 2020).
cerebral tumor (1 paper, 2021). "In tumor-bearing nude mice, using doxycycline-dependent GliPR1 knockdown, subcutaneous and cranial transplantation of the U87-MG clone 980-5 (transduced with GliPR1 sh#301) resulted in reduced subcutaneous tumor volume and cerebral tumor area in doxycycline-treated mice versus those left untreated." (PMID 33856615, 2021).
diabetes (1 paper, 2025). "Notably, SREK1 and GLIPR1 were commonly detected across all four tissues, suggesting potential systemic regulators of diabetes-related complications." (PMID 41208460, 2025).
gastric cancer (1 paper, 2024). A primary or metastatic malignant neoplasm involving the stomach. "CAR-T cell functions were detected in vitro and in vivo after GLI Pathogenesis Related 1 (GLIPR1) knockdown in gastric cancer cells." (PMID 38368374, 2024). "Collectively, GLIPR1 knockdown in gastric cancer cells enhanced the cytotoxicity and cytokine production of CAR-T cells in vitro and in vivo." (PMID 38368374, 2024). "With stable suppression of GLIPR1 in HGC27, both CAR-T cells increased cytotoxicity against cancer cells and cytokine production of IFN-γ and IL-2, suggesting CAR-T cells displayed better functions in gastric cancer with GLIPR1 knockdown." (PMID 38368374, 2024). "Collectively, GLIPR1 knockdown inhibited gastric cancer cell proliferation and migration, while GLIPR1 overexpression improved cancer development, suggesting a promising immunotherapy target in combined strategy." (PMID 38368374, 2024). "Our data demonstrated for the first time that this CAR structure design combined with GLIPR1 knockdown in gastric cancer improved CAR-T cell-mediated anti-tumor response." (PMID 38368374, 2024). "Given that membrane proteins were easier to target in therapy, GLIPR1 were chosen for further research, which was an oncogene or tumor-suppressed genes in different cancers, but barely understood in gastric cancer." (PMID 38368374, 2024). "GLIPR1 was up-regulated after CAR-T treatment and survival was decreased in gastric cancer patients with high GLIPR1 expression." (PMID 38368374, 2024). "Cell proliferation and migration of gastric cancer cells were detected by CCK-8 and scratch assay respectively after GLIPR1 were overexpressed or down-regulated." (PMID 38368374, 2024). "As for CXCR4 and GLIPR1, they were up-regulated in our results and in STAD patients, indicating their oncogenic effect on gastric cancer." (PMID 38368374, 2024).
hepatocellular carcinoma (1 paper, 2025). A malignant tumor that arises from hepatocytes. "Notably, in hepatocellular carcinoma, GLIPR1 activates the PI3K/PDK1/ROCK1 signaling axis, thereby enhancing EMT, cellular motility, and resistance to 5-fluorouracil." (PMID 41208460, 2025).
Insulin resistance (1 paper, 2023). Increased resistance towards insulin, that is, diminished effectiveness of insulin in reducing blood glucose levels. "Moreover, RNA sequencing of adipose tissue in PCOS patients has identified GLIPR1 to be differentially expressed according to genotype near PCOS risk loci, suggesting a possible relationship between insulin resistance and fertility." (PMID 37261354, 2023).
lymph node metastasis (1 paper, 2015). "The finding that the incidence of lymph node metastasis was significantly lower in animals treated with the combination treatment than in control-treated animals is consistent with our in vitro data and may be related to the inhibition of the docetaxel-induced ERK1/2-CXCR4-c-Myc axis by GLIPR1-ΔTM." (PMID 26084402, 2015).
multiple myeloma (1 paper, 2020). "This is consistent with the previously reported down-regulation of GLIPR1 expression in the PCs of light-chain amyloidosis patients compared with normal controls, suggesting that this may be a common genetic event in PC malignancies." (PMID 31995627, 2020).
non-small cell lung carcinoma (1 paper, 2024). A group of at least three distinct histological types of lung cancer, including non-small cell squamous cell carcinoma, adenocarcinoma, and large cell carcinoma. "miR-301a regulated glioma pathogenesis-related protein 1 (GLIPR1) expression in non-small cell lung cancer, which contributed to cisplatin resistance." (PMID 38360723, 2024).
plasmacytoma (1 paper, 2020). Plasmacytoma is a localized mass of neoplastic monoclonal plasma cells that represents approximately 5% of all plasma cell neoplasms. "Notably, 40% of the tumours in the Glipr1-/- mice were classified as plasmacytomas, a localised PC malignancy that frequently progresses to MM." (PMID 31995627, 2020).
stomach adenocarcinoma (1 paper, 2024). "RNA sequencing of the remaining cancer cells after low-efficiency target cell killing revealed that GLI Pathogenesis Related 1 (GLIPR1) was up-regulated and high expression of GLIPR1 decreased survival rate of stomach adenocarcinoma (STAD) patients." (PMID 38368374, 2024).
type A thymoma (1 paper, 2020). "The upstream regulator analysis showed these differential proteins with their overexpression in type A thymoma were likely regulated by HBEGF, LEF1, and GLIPR1." (PMID 31967407, 2020).
tumor (35 papers, 2008 to 2025). "Adenoviral vector-mediated GLIPR1 therapy in an immunocompetent orthotopic prostate mouse model showed significantly reduced tumor-associated angiogenesis." (PMID 26988096, 2016). "In contrast, in astrocytes-derived tumors over-expression of GLIPR1 is associated with an enhancement in cellular proliferation and tumor invasion, while GLIPR1 silencing is associated with an elevated level of apoptosis." (PMID 26302043, 2015). "GLIPR1 has been associated with variable functions in humans, such as cell proliferation, apoptosis and tumor growth." (PMID 26302043, 2015). "Given that the down-regulation of tumour suppressor genes by hypermethylation of promoter CpG sites is a common feature of MM PCs, it is possible that this mechanism underlies reduced GLIPR1 expression in at least some patients." (PMID 31995627, 2020). "As Glipr1 overexpression in MM PCs caused a trend towards reduced tumour growth in the aggressive KaLwRij-5TGM1 model, we hypothesised that the loss of Glipr1 expression in mice may promote the development of premalignant and/or malignant PC expansions." (PMID 31995627, 2020). "In cancer contexts, GLIPR1 has been shown to promote tumor proliferation, metastasis, and chemoresistance." (PMID 41208460, 2025). "In all cases, GLIPR1 demonstrated tumour suppressor activity in vitro, and, furthermore, GLIPR1 expression was shown to suppress prostate cancer tumour growth in vivo." (PMID 31995627, 2020). "While Glipr1 mRNA expression was detected in normal PCs from both the WT and KaLwRij mouse strains, Glipr1 expression was undetectable in the 5TGM1 MM PC line, consistent with Glipr1 being a tumour suppressor." (PMID 31995627, 2020). "Several of these proteins have tumor suppressor function in human and other animals, namely Wilms Tumor 1 Associated Protein (WT1), Heat Shock Protein 90 (HSP90), Glioma Pathogenesis-Related Protein 1 (GLIPR1) and Matrix Metalloproteinase B (Smed-MMPB)." (PMID 29967069, 2018). "The addition of GLIPR1-ΔTM to docetaxel was found to decrease the migration of PCa cells while this combination additively decreased tumor growth and metastatic potential in VCaP xenografts." (PMID 26084402, 2015). "Combination treatment decreased IVIS signal than GLIPR1-ΔΤΜ did and decreased significantly tumor weight than both single-agent treatments did." (PMID 26084402, 2015). "The combination treatment with docetaxel and GLIPR1-ΔTM inhibited tumor growth and decreased metastatic potential in VCaP xenografts more than single agents did." (PMID 26084402, 2015). "Increased apoptosis, accompanied by decreased tumor progression and metastasis were reported following adeno-viral delivery of Glipr1 in an orthotopic model for metastatic prostate cancer." (PMID 24010123, 2013). "This study is one of the first to reveal the histone code and MBD profile at the promoters of CD44, Cyclin D2, GLIPR1 and PTEN in different tumour cells and associated changes after stimulation with methylation inhibitor 5-aza-CdR." (PMID 20565761, 2010). "In the current study, the participation of MBDs in the transcriptional repression of the four selected tumour-associated genes CD44, Cyclin D2, GLIPR1 and PTEN was examined." (PMID 20565761, 2010). "In addition, GLIPR1 has been implicated in the regulation of epithelial–mesenchymal transition (EMT), cancer cell motility, and anti-tumor immune responses through pathways such as PI3K/PDK1/ROCK1." (PMID 41208460, 2025). "CAR-T treatment combined with GLIPR1 knockdown increased anti-tumor efficacy in vitro and in vivo." (PMID 38368374, 2024).
tumor (continued). "This experiment confirmed the anti-tumor effect of doxycycline-induced GliPR1 knockdown." (PMID 33856615, 2021). "Given the integral role of the BM microenvironment on MM tumour development and the inability to fully recapitulate its complexities in vitro, the 5TGM1/KaLwRij murine model of MM was used to assess the effect of Glipr1 re-expression on MM tumour growth in vivo." (PMID 31995627, 2020). "The putative tumour suppressor role of GLIPR1 is further supported by the finding that Glipr1-/- mice had reduced survival due to increased rates of spontaneous malignancy, although tumour development was of late onset (after ~500 days) and incomplete penetrance (~40%)." (PMID 31995627, 2020). "Together, these data support a potential tumour suppressor role for GLIPR1 in MM." (PMID 31995627, 2020). "GLIPR1 is a pleiotropic protein involved in cell proliferation, tumor growth and apoptosis, and it may affect G protein signaling and cell cycle regulation." (PMID 24810788, 2014). "In the present study, the promoters of the four above-described tumour-associated genes (CD44, Cyclin D2, GLIPR1 and PTEN) were examined for methylation-dependent gene regulation, the participation of MBDs in gene silencing and the histone modifications associated with the respective promoter areas." (PMID 20565761, 2010). "The reduced Ccl5 secretion associated with Glipr1 knockdown led to reduced tumour infiltration by inflammatory macrophage and CD8+ T cytotoxic T cells, thereby aiding tumour immunity, as infiltration by these immune cells is usually associated with reduced tumour growth." (PMID 34572888, 2021). "For example, the glioma pathogenesis-related protein 1 gene (GLIPR1; MIM #602692), which also acts as a tumour suppressor, shows strong promoter hypermethylation and is downregulated in AT/RT." (PMID 40794298, 2025). "In transgenic mouse models of FTC, a mechanism was found that advanced cancer in emasculated men was due to increased expression of tumor suppressor genes:GLIPR1 and SFRP1, resulting in increased tumor invasion of M1-macrophages and CD8 cells." (PMID 35479325, 2022). "Altogether, our data suggest that both GLIPR1 and MMPB have tumor suppressor function in S. mediterranea, as their downregulation led to the development of macroscopic dysplastic lesions affecting the entire body of the animal." (PMID 29967069, 2018). "Pro-apoptotic activities have been described for GLIPR1 and MAFB that were upregulated in immortalized keratinocytes and HPV+ tumor cells." (PMID 23702334, 2013). "Therefore although the GLIPR1 hypomethylation observed in WTs might reflect an expansion of oncofetal cells lacking GLIPR1 methylation, hypermethylation of PCDHs and other tumour suppressor genes appears to represent a later, tumour-specific lesion." (PMID 19956686, 2009). "With GLIPR1 down-regulation in HGC27, tumor cell proliferation was inhibited." (PMID 38368374, 2024). "This experiment thus confirmed that the anti-tumor effect seen with doxycycline-induced GliPR1 knockdown also occurs with stable GliPR1 knockdown (i.e. in the absence of any doxycycline effect)." (PMID 33856615, 2021). "In addition, we demonstrate that Glipr1 expression is lost in the C57BL/KaLwRij-5TGM1 murine model of MM and assess the impact of its reintroduction on tumour growth in vivo." (PMID 31995627, 2020). "Notably, five DEG expression levels were correlated with prognosis in these three tumor types, including AXL, CCDC152, EVI2B, GLIPR1, and SERPING1." (PMID 32903590, 2020). "Despite this, the overexpression of GLIPR1/Glipr1 in a HMCL/5TGM1 cells did not significantly alter tumour cell growth in vitro or in vivo." (PMID 31995627, 2020). "In contrast, neither the overexpression of GLIPR1 in the H929 HMCL nor the re-expression of Glipr1 in the 5TGM1 murine MM cell line affected basal tumour cell proliferation or colony formation in vitro." (PMID 31995627, 2020).
tumor (continued). "Together these results suggest that GLIPR1 is unlikely to be a potent tumour suppressor in MM, but further work is required to determine whether its down-regulation may contribute to disease development." (PMID 31995627, 2020). "In the context of murine MM, the expression of Glipr1 was found to be absent in the KaLwRij tumour-derived 5TGM1 MM cell line compared to detectable levels in PCs from healthy KaLwRij and WT mice, suggesting that Glipr1 down-regulation may also play a role in the development of murine MM." (PMID 31995627, 2020). "With stable overexpression of GLIPR1 in HGC27, cytotoxicity of 15B6 CAR-T was inhibited while 15B6ss CAR-T was not affected, suggesting better tumor-killing capacity of CAR-ss-T cells." (PMID 38368374, 2024). "The overexpression of GLIPR1 did not inhibit the cytotoxicity of CAR-ss-T significantly, suggesting the potential of this structure against tumor resistance." (PMID 38368374, 2024). "However, the low penetrance (~17%) and late onset (no mortality until at least 15 months of age) of tumours in these mice suggests that the cohort size and length of monitoring of the Glipr1-/- mice in this study may have been insufficient to observe potentially enhanced PC tumorigenesis." (PMID 31995627, 2020).